RPL5 (ribosomal protein L5)
Diseases named in the same sentence as RPL5 in open-access papers (continued):
Sharing a sentence is not in itself a finding about the gene and the disease.
Diamond-Blackfan anemia (25 papers, 2010 to 2025). A congenital aregenerative and often macrocytic anemia with erythroblastopenia. "For instance, studies in Diamond-Blackfan anemia (DBA) demonstrated that mutations in 60S or 40S ribosomal proteins [such as RPL5, RPL11, RPS7, RPS10 among others] decrease the ribosome levels but leave the composition of the ribosomes intact." (PMID 30697227, 2018). "In Diamond-Blackfan Anemia, loss-of-function in RPL5, L11 or L26, or RPS7, S17, S19, or S26 is associated with Cathie facies, short stature, and upper limb, heart, and urogenital anomalies." (PMID 28046103, 2017). "Another ribosomal protein-coding gene RPL5, where over 15 different mutations have been identified so far, is associated with Diamond-Blackfan anemia (DBA), an inherited bone marrow failure syndrome." (PMID 30577491, 2018). "Further, mutations in several ribosomal protein (RP) genes, such as RPS19, RPL5, RPL11, RPL35A, RPS10, RPS17, and RPS24, cause Diamond-Blackfan anemia (DBA)." (PMID 38820160, 2024). "Mutations in specific RPs, such as RPL5, RPL11, RPS17, RPS19, and RPS24, have been associated with Diamond Blackfan Anemia (DBA)." (PMID 39086661, 2024). "There are abundant genetic and experimental evidences demonstrate that Diamond-Blackfan anemia (DBA), a dominant autosomal bone marrow failure syndrome, is due to mutations in ribosomal genes including RPS19, RPS24, RPL5, RPL11, and RPS29, etc8-12." (PMID 31523176, 2019). "In humans, mutations in RPs have been implicated in hematopoetic disorders, most notably Diamond-Blackfan anemia (DBA), which has been attributed to mutations in RPS19, RPS26, RPS24, RPS17, RPS10, RPS7, RPL35a, RPL26, RPL11, and RPL5." (PMID 23382688, 2013). "One notable syndrome is Diamond-Blackfan anemia (DBA) caused by mutations in ribosomal proteins (RPS19, RPL11, RPL5 and others) leading to defective 40S or 60S ribosomal subunit production with elevated risk of leukemia and osteosarcoma." (PMID 21152184, 2011). "For example, the Diamond-Blackfan Anemia (DBA) is caused by heterozygous loss-of-function mutations in genes encoding RPs, such as RPS19, RPL5, and RPL11, while the 5q-syndrome is caused by a somatically acquired deletion of chromosome 5q, which leads to haploinsufficiency of RPS14." (PMID 30862090, 2019). "The patient tested negative for pathogenic variants in genes associated with Diamond-Blackfan anemia: RPS19, RPL5, RPL11, RPS26, RPL35a, and RPL15." (PMID 35774100, 2022). "The most well characterized is Diamond Blackfan anemia (DBA), which results from haploinsufficiencies in several different RP genes (RPS24/eS24, RPS17/eS17, RPL35A/eL33, RPL5/uL18, RPL11/uL5, RPS7/eS7, RPL36/eL36, RPS15/uS19, RPS27A/eS31) and RPS19/eS19, which is mutated in 25% of patients." (PMID 33565275, 2021).
melanoma (15 papers, 2014 to 2025). A malignant, usually aggressive tumor composed of atypical, neoplastic melanocytes. "However, a G201V RPL5 mutation has been described in malignant melanoma." (PMID 36482893, 2022). "RPS27 contains a mutational hotspot in its 5’UTR in melanoma (SKCM), and we showed that RPL5 is part of a minimal deleted region that is heterozygously deleted in 20-40% of advanced multiple myeloma cases." (PMID 28147343, 2017). "Interestingly, RPL5 is determined to act tumor suppressive in various cancer types, also melanoma and RPL34 seems to be tumour suppressive in esophageal cancer." (PMID 35883595, 2022). "According to Oncomine database DR1, EVI5, TMED5 and RPL5 are co-amplified also in brain, colon, lung cancer and melanoma, indicating that amplification of 1p21-22 may be a recurrent alteration in several different types of cancers." (PMID 25135188, 2014).
glioblastoma (13 papers, 2014 to 2024). The most malignant astrocytic tumor (WHO grade IV). "We found that HMGB3 and YBX1 were predicted to target 11 risk genes for glioblastoma, including RPL5 and IDH1, as shared target genes." (PMID 39363111, 2024). "The frequency of inactivating RPL5 mutations and deletions was found to be 11% in glioblastoma, 28% in melanoma, and 34% in breast cancer patients." (PMID 29855342, 2018). "Regarding the RPs of the large ribosome subunit, exome sequencing demonstrated the presence of mutations of RPL5 in T cell acute lymphoblastic leukemia (T-ALL) and in glioblastoma, and loss of the 1p22.1 region encompassing the RPL5 gene was found in 20% of multiple myeloma cases (MM)." (PMID 29855342, 2018). "For example, with glioblastoma, eS6 (RPS6), eS27 (RPS27), uS8 (RPS15A) and eL34 (RPL34) are known as oncogenic, whereas uL18 (RPL5), uS17 (RPS11), uS9 (RPS16) and uS13 (RPS18) are found to have a tumor-suppressive function." (PMID 37511213, 2023).
T-cell acute lymphoblastic leukemia (13 papers, 2015 to 2023). Acute lymphoblastic leukemia of T-cell origin. "In fact, mutations in ribosomal protein-coding genes have been reported in the literature in relation to T-cell acute lymphoblastic leukemia (RPL5 and RPL11) and gliomas (RPL5)." (PMID 36865483, 2023). "In this regard, it is interesting that frequent mutations in RPL5 and RPL10 or in CNOT3 have been observed to accumulate in adult T-cell acute lymphoblastic leukemia (T-ALL)." (PMID 28588606, 2017). "These recent exome sequencing reports have identified mutations in RPL5 and RPL10 in T-cell acute lymphoblastic leukemia, mutations in RPL5 in gliomas, and mutations in RPL22 in human endometrioid endometrial cancer and colorectal cancer." (PMID 26132763, 2015).
colorectal cancer (10 papers, 2013 to 2025). A primary or metastatic malignant neoplasm that affects the colon or rectum. "The results indeed revealed that the CS&Z-induced inhibition of c-Myc was reversed following the loss of RPL5, thereby tending to indicate that the CS&Z-regulated expression of c-Myc in colorectal cancer cells is mediated via RPL5." (PMID 40429805, 2025). "Compared with other plant-derived anticancer agents, CS&Z targets the RPL5–c-Myc axis in colorectal cancer and also potentiates the effects of conventional chemotherapeutics, offering a potentially therapeutic advantage." (PMID 40429805, 2025). "CS&Z has been identified as a candidate for such an approach, demonstrating for the first time its ability to induce apoptosis in colorectal cancer cells via RPL5-mediated inhibition of the oncogene c-Myc." (PMID 40429805, 2025). "On the basis of our findings, we propose that CS&Z induces apoptosis in colorectal cancer cells, primarily via RPL5-mediated regulation of the oncogene c-Myc." (PMID 40429805, 2025). "Increased expression of ribosomal protein genes including rpS3, rpS6, rpS8, rpS12 and rpL5 has been reported in colorectal cancer." (PMID 32973493, 2020). "Therefore, to confirm whether the CS&Z-induced inhibition of c-Myc is mediated via RPL5 in colorectal cancer cells, we transfected cells with RPL5 siRNA and assessed the effects of silencing RPL5 on c-Myc expression." (PMID 40429805, 2025). "Although the role of this protein in cancer is highly speculative, overexpression of ribosomal protein L5 has been identified in several colorectal cancer cases, which suggests a potential significance of the protein in tumor development or resistance to antineoplastic drugs." (PMID 23755301, 2013). "For example, the expression of RPL5, RPS3, RPS6, RPS8, and RPS12 in colorectal cancer was higher than that in normal colorectal mucosa." (PMID 33584809, 2020). "In addition, mutations in the ribosomal protein genes have been found to be involved in cancers such as endometrial cancer (RPL22), chronic lymphoblastic leukemia (RPS15), colorectal cancer (RPS20), and glioma (RPL5)." (PMID 34827869, 2021).
multiple myeloma (10 papers, 2017 to 2023). "A low level of RPL5 expression in multiple myeloma patients was correlated with a higher relapse rate following bortezomib treatment." (PMID 37016705, 2023). "RPL5 was significantly down-regulated in multiple myeloma patients as compared with healthy controls." (PMID 33668794, 2021). "In addition, RPL5 shows inactivating mutations in 2% of T-ALL samples and we showed that RPL5 is part of a minimal deleted region that is heterozygously deleted in 20-40% of advanced multiple myeloma cases." (PMID 28147343, 2017).
acute lymphoblastic leukemia (8 papers, 2017 to 2022). Leukemia with an acute onset, characterized by the presence of lymphoblasts in the bone marrow and the peripheral blood. "Exome sequencing revealed mutations in CNOT3 and the ribosomal genes RPL5 and RPL10 in acute lymphoblastic leukemia." (PMID 36147491, 2022). "Indeed, mutations in CNOT3, the ortholog of Not5, or in the RPL5 and RPL10 ribosomal proteins, are associated with adult T-cell acute lymphoblastic leukemia (T-ALL)." (PMID 28588606, 2017).
lung carcinoma (8 papers, 2014 to 2023). "uL5/RPL11 and uL18/RPL5 also contribute strongly to the maintenance of nucleolar structure in cell lines for colon cancer (HCT116) and lung cancer (A549 and H1944)." (PMID 37047306, 2023).
colon cancer (6 papers, 2021 to 2025). "Reducing RPL5 levels hinders the growth and migration of colon cancer cells and causes cell cycle arrest." (PMID 38255260, 2024). "One illustrative example is represented by an increased expression level of RPL5 in colon cancer, revealing its significant contribution to proliferation and migration." (PMID 38255260, 2024). "In summary,RPL5 regulates colon cancer cell proliferation and migration through MAPK/ERK signaling pathway." (PMID 36384455, 2022). "This study suggests that RPL5 can be a potential therapeutic target for clinical treatment of colon cancer patients." (PMID 36384455, 2022). "In our study, it was found that RPL5 is highly expressed in colon cancer, and more importantly, RPL5 regulates colon cancer proliferation and migration through the MAPK/ERK signaling pathway." (PMID 36384455, 2022). "The expression level of RPL5 in colon cancer tissues and cell lines was significantly higher than that in adjacent tissues and NCM460 cells, respectively, and its expression level was higher in HCT116 cells and RKO cells." (PMID 36384455, 2022). "The TCGA database was used to analyze the correlation between the expression of RPL5 and the stage of clinical colon cancer patients, and the results showed that the expression of RPL5 was correlated with the stage of the patients." (PMID 36384455, 2022). "To further confirm the role of RPL5 in colon cancer, we designed interference fragments targeting RPL5 (siRPL5) and control (siNC), and western blotting and RT-qPCR were used to verify the transfection efficiency of HCT116 and RKO cells." (PMID 36384455, 2022). "The effect of RPL5 on the cell cycle of colon cancer cells was observed by flow cytometry, and it was found that compared with the siNC-transfected group, the cell cycle was arrested in the G0/G1 phase after siRPL5 transfection." (PMID 36384455, 2022). "RPL5 is involved in the progression of various malignancies, however, the role of RPL5 in colon cancer remains is still unclear." (PMID 36384455, 2022). "The effects of RPL5 on the proliferation of colon cancer cell lines HCT116 and RKO were investigated by CCK-8 assay and cell clone formation assay." (PMID 36384455, 2022). "In order to further observe the effect of RPL5 on the migration ability of colon cancer cells, wound healing assay was performed." (PMID 36384455, 2022). "Compared with normal colon epithelial cell lines NCM460, the protein levels of RPL5 were increased in colon cancer cell lines." (PMID 36384455, 2022). "Depletion of 60 S ribosomal protein L5 (RPL15) caused ribosomal stress, resulting in apoptosis in colon cancer cells." (PMID 33499187, 2021). "RPL5 regulates colon cancer proliferation and migration through MAPK/ERK signaling." (PMID 41463151, 2025). "Additionally, an ERK activator (TBHQ) can partially reverse these effects, suggesting RPL5’s role in promoting colon cancer cell proliferation and migration via this pathway." (PMID 38255260, 2024). "The expression of RPL5 in clinical colon cancer tissues was detected by western blotting, and the results showed that compared with adjacent tissues, the expression of RPL5 in colon cancer tissues increased." (PMID 36384455, 2022). "In order to explore the potential mechanism of RPL5 regulation of colon cancer cell proliferation and migration, this study firstly detected the changes of MAPK/ERK signaling pathway-related proteins in the siRPL5 transfection experimental system by western blotting." (PMID 36384455, 2022). "Thus, we conclude that the promoting effect of RPL5 on colon cancer cell lines may be, at least in part, due to the activation of MAPK/ERK signaling." (PMID 36384455, 2022).
colon cancer (continued). "To further confirm that RPL5 regulates colon cancer cell proliferation and migration through MAPK/ERK signaling pathway, we observed whether TBHQ could reverse or partially reverse the inhibitory effect of siRPL5 on colon cancer cell proliferation and migration by CCK8 assay and wound healing assay." (PMID 36384455, 2022). "However, the role and regulation mechanism of RPL5 has not been revealed in colon cancer." (PMID 36384455, 2022).
hepatocellular carcinoma (5 papers, 2021 to 2025). A malignant tumor that arises from hepatocytes. "For example, the upregulation of SNORA18L5 in hepatocellular carcinoma (HCC) led to hyperactive ribosome biogenesis, increasing levels of mature rRNAs that in turn caused the accumulation of the ribosomal proteins RPL5 and RPL11 in the nucleolus." (PMID 34638533, 2021). "Furthermore, researchers studied the oncogenic potential of MID1IP1 in hepatocellular carcinoma cell (HCC) growth in relation to ribosomal protein L5 and L11 and CNOT2-mediated c-Myc signaling and found that CNOT2 knockdown could further inhibit the downregulation of MID1IP1 by c-Myc." (PMID 40864769, 2025).
leukemia (5 papers, 2020 to 2025). A malignant (clonal) hematologic disorder, involving hematopoietic stem cells and characterized by the presence of primitive or atypical myeloid or lymphoid cells in the bone marrow and the blood. "Exome sequencing and other approaches have further shown that mutations in RPL5 (uL18), RPL10 (uL16), RPL11 (uL5), RPL22 (eL22), RPS15 (uS19) and RPS20 (uS10) are present in a variety of cancers, especially leukaemia." (PMID 37526268, 2023). "Further analysis is necessary to understand the differences in RPL5 mechanisms of action in leukemias compared to other cancer types regarding its role in prognosis." (PMID 36497424, 2022). "We used K562 leukemia cell line to examine the impacts of reduced levels of specific RP transcripts, RPS10, RPL35A (the ortholog of C. elegans rpl-33), RPL5, and RPS23." (PMID 39786340, 2025). "RPL5 knockdown reduced the survival and colony-forming ability of AML cells in vitro, as well as inhibited the engraftment of leukemia stem cells (LSCs) in vivo." (PMID 41413025, 2025).
breast invasive cancer (3 papers, 2017 to 2022). "According to the data of StarBase database, RPL5 was downregulated in breast invasive cancer." (PMID 35293275, 2022). "Furthermore, in breast invasive carcinoma (BRCA), RPL5 was significantly heterozygously deleted in 33.9% of cases." (PMID 28147343, 2017).
COVID-19 (3 papers, 2022 to 2024). A disease caused by infection with severe acute respiratory syndrome coronavirus 2. "Also, spec_24h mRNAs were enriched in 12 KEGG terms such as Coronavirus disease-COVID-19, Ribosome, MAPK signaling pathway, Cytokine-cytokine receptor interaction, Focal adhesion, involving genes such as Rpl7, Rpl3, Rpl5, Rpl4, Rps15a." (PMID 38622534, 2024).
acute myeloid leukemia (2 papers, 2016 to 2025). Acute myeloid leukemia (AML) is a group of neoplasms arising from precursor cells committed to the myeloid cell-line differentiation. "Particularly, the specific role of RPL5 in acute myeloid leukemia (AML) remains unclear." (PMID 41413025, 2025).
anemia (2 papers, 2019 to 2023). A reduction in the number of red blood cells, the amount of hemoglobin, and/or the volume of packed red blood cells. "After 2 weeks of treatment, a mild anemia was detected in about 20% of the treated shRNA Rpl5 mice while controlmice were normal." (PMID 32309614, 2019).
breast tumors (2 papers, 2018). "This evolution is mediated in part by ribosomal alterations that are driven by mutations in uL18/RPL5 ribosomal protein genes in ~34% of breast tumors." (PMID 30545127, 2018). "RPL5 has also been reported to play tumor suppressor roles in breast tumors." (PMID 30479569, 2018).
colon adenocarcinoma (2 papers, 2022 to 2023). "This study examines the effect of RPL5 on the progression of colon adenocarcinoma (COAD), including cell proliferation, migration and determines its underlying molecular mechanism using CRC cell lines in vitro." (PMID 36384455, 2022).
liver cancer (2 papers, 2020 to 2022). An epithelial or non-epithelial malignant neoplasm that arises from the liver. "Taken together, these findings provide novel insight that MID1IP1 promotes the growth of liver cancer via colocalization with c-Myc mediated by ribosomal protein L5 and L11 and CNOT2 as a potent oncogenic molecule." (PMID 32316188, 2020). "Overall, these findings suggest that MID1IP1 promotes liver cancer progression via colocalization with c-Myc mediated by ribosomal protein L5 and L11 and CNOT2 as a potent oncogenic molecule." (PMID 32316188, 2020).